FUS (FUS RNA binding protein)
Diseases named in the same sentence as FUS in open-access papers (continued):
Sharing a sentence is not in itself a finding about the gene and the disease.
Ewing sarcoma (continued). "In fact, several reports have indicated that LLPS might play a role in aberrant gene expression linked to leukemogenesis in the case of EWS–FLI1, a driver in Ewing sarcoma, and other FUS/EWS/TAF15 protein family FOs." (PMID 34903620, 2022). "The FUS forward primer was designed within exon 3 to detect unusually short fusion genes, although no fusion with a shorter FUS 5′-terminal side sequence were reported in Ewing sarcoma." (PMID 34749732, 2021). "Detection of the tumor-specific EWSR1/FUS-ETS fusion gene is essential to diagnose Ewing sarcoma." (PMID 34749732, 2021). "Interestingly, all the described EWSR1-ERG and FUS-ERG fusions in the small round blue cell tumor/Ewing sarcoma groups involve a breakpoint situated in exons 8, 9, 10, and 11 further downstream toward the 3′ end of ERG." (PMID 31906059, 2019). "In the present study, tumor from a patient with a Ewing's sarcoma with cyclin-dependent kinase inhibitor 2A/B (CDKN2A/B) loss and FUS-ERG fusion was implanted in the right chest wall of nude mice to establish a patient-derived orthotopic xenograft (PDOX) model." (PMID 27286459, 2016). "Poor prognostic features were found in two other patients: low expression of PAX8, FHIT, CASP10, CHD2, with high expression of CHD11, FUS, and MTA1 in a patient with Ewing sarcoma, and gain of 1q and loss of 6q and overexpression of TNC, CALB1, PLAG1, ALDH1L1, and RELN in a patient with ependymoma." (PMID 28007021, 2016). "Notably, two of the FUS studies also investigated related proteins belonging to the FET protein family: TATA-binding protein-associated factor 2 N (TAF15) and Ewing’s sarcoma (EWS)." (PMID 41341655, 2025). "The FUS‐ERG fusion occurs primarily in acute myeloid leukemia patients, though rarely it has been seen in myeloid sarcoma tumors and Ewing sarcomas." (PMID 40285687, 2025). "This TF is well known for its role in oncogenic gene fusion products in multiple cancers including prostate cancer (TMPSSR2-ERG and NDRG1-ERG), in Ewing’s sarcoma (EWS-ERG) and acute myeloid leukemia (FUS-ERG)." (PMID 40453647, 2025). "A gene fusion of one of the FET family RNA-binding proteins, including EWSR1 and FUS genes as 5⁣′ partners, and one of the ETS family transcription factors as 3⁣′ partners, is the defining genetic characteristic of essentially all Ewing sarcoma cases." (PMID 40861426, 2025). "Examination of these DRIP-seq data reveal that there is a differential enrichment in R-loops in the MSC lineage at the loci involved in the translocations described in Ewing sarcoma, such as EWSR1, FLI1, or FUS (personal observation, Figure A1 in Appendix A)." (PMID 38339014, 2024). "Fifteen Ewing sarcoma PDX were established, 13 displayed the EWSR1::FLI1 translocation, one each FUS::ERG and EWSR1::FEV." (PMID 37723198, 2023). "Hematopoietic-associated fusions involving ERG also extend to EWSR1-ERG in 5-10% of Ewing’s sarcoma, and ELF4-ERG and FUS-ERG in acute myeloid leukemia." (PMID 37377909, 2023). "It was later reported that Ewing sarcoma has more chromosomal translocations, including EWS/FLI fusion, EWS/ERG fusion, EWS/FEV fusion, EWS/ETV1 fusion, EWS/ETV4 fusion, FUS/ERG fusion, FUS/FEV fusion, and FUS/ETV4 fusion." (PMID 36964542, 2023). "We identified EWSR1/FUS-ETS fusion transcripts in all cell lines and pathologically defined Ewing sarcoma tumors that were tested." (PMID 34749732, 2021). "Further, mouse mesenchymal cells transformed with either the EWS-FLI1 or FUS-CHOP rearrangement displayed similar sensitivities to olaparib, whereas the Ewing’s sarcoma cell line SK-N-MC had increased olaparib sensitivity." (PMID 29313488, 2018). "Five different FUS-ERG transcript types have been reported in AML, and three additional types in Ewing tumors (types 4, 5, 8, 9, 31)." (PMID 24068373, 2013). "The Ewing's sarcoma EWS-FLI1, EWS-ERG and FUS-ERG fusion genes, the AML FUS-ERG fusion and the human FLI1 and ERG1 genes were RT-PCR amplified as described in materials and methods." (PMID 18648544, 2008).
Ewing sarcoma (continued). "Ewing’s sarcoma is a malignant small round cell tumor in which chromosomal translocations between genes of the E26 transformation specific (ETS) family, and TET/FET (TLS/FUS, EWSR1 and TAF15) family are frequently detected (Riggi and Stamenkoviç, 2007)." (PMID 38954213, 2025). "In routine pathological practice, Ewing sarcoma with atypical morphology or small round cell sarcoma without typical EWSR1/FUS-ETS fusions is occasionally observed." (PMID 34749732, 2021). "Both ESWSR1-NFATC2 and FUS-NFATC2 fusion-carrying tumors do not show microscopical or clinical features of Ewing sarcoma." (PMID 31049020, 2019). "This FET-ETS fusion between a member of the FET family of genes, usually EWSR1 or FUS, and a member of the ETS (E26 transformation-specific or erythroblast transformation-specific) family of transcription factors, such as FLI1 or ERG, is a marker of Ewing sarcoma." (PMID 40255709, 2025). "FUS is highly related to EWSR1, and both are members of the FET (FUS/TLS, EWS, and TAF15) family of RNA binding proteins, while FLI1 and its related genes are members of the ETS family of DNA binding proteins, and together the “FET-ETS” fusions represent nearly all cases of Ewing sarcoma." (PMID 33488267, 2020). "However, a negative FISH analysis does not exclude a diagnosis of Ewing sarcoma as the fusion protein may include FUS, a cryptic ESWR1, or ESWR1-ERG." (PMID 40255709, 2025). "Additional cytogenetic and molecular studies confirmed the presence of the CBFA2T3::GLIS2 fusion, but no Ewing sarcoma-specific EWSR1, FUS and CIC fusion transcripts were found." (PMID 40565358, 2025). "The result of RNA sequencing showed that no fusion genes related to Ewing’s sarcoma (including EWSR1-FLI1, EWSR1-ERG, EWSR1-ETV1, EWSR1-ETV4, EWSR1-FEV, FUS-ERG, FUS-FEV) were detected." (PMID 35568949, 2022). "No Ewing sarcoma-specific EWSR1, FUS and CIC fusion transcripts were found." (PMID 40565358, 2025).
proteinopathies (58 papers, 2011 to 2025). "Nevertheless, ALS animal models with mutations in genes coding for this protein, the so-called FUS proteinopathies, have been increasingly proposed." (PMID 36836867, 2023). "As a broadly consistent ALS disease phenotype is associated with either TDP-43, SOD1, or FUS proteinopathies, it is likely they reflect earlier events which promotes aggregation amongst other neurotoxic effects." (PMID 35002606, 2021). "Studies in yeast models demonstrated that expression of ALS-associated FUS mutants can lead to protein aggregation and cytotoxicity that recapitulate FUS proteinopathy." (PMID 24204307, 2013). "We find that expression of a disease-associated FUS mutation (FUSΔ14) validates it as a pathogenic mutation, because expression of this mutation produced a number of pathological features of FUS proteinopathies." (PMID 23046583, 2012). "Although FUS mutations obviously affect MNs as well as other neurons found in FUS transgenic D. melanogaster models, its pathogenic mechanism of proteinopathy remains largely unknown." (PMID 38500677, 2024). "It remains unclear whether the loss of or gain of function of FUS is involved in the pathogenesis of FUS proteinopathies." (PMID 35753345, 2022). "A large number of animal models have been employed to elucidate the underlying molecular mechanisms of FUS-proteinopathies, and Drosophila melanogaster has been utilized to discern some important aspects of their pathogenesis due to the conservation of FUS protein functions during evolution." (PMID 29142303, 2017). "Our data also suggest that mitochondrial damage may be a target in future development of diagnostic and therapeutic tools for FUS-proteinopathies, a group of devastating neurodegenerative diseases." (PMID 26335776, 2015). "Thus, iNeurons may provide a more reliable model for investigating FUS mutations with disrupted NLS for understanding FUS-associated proteinopathies in ALS." (PMID 26795035, 2016). "Altogether, it is plausible that both mechanisms – loss-of-function in the nucleus and gain-of-toxicity in the cytoplasm – synergistically drive neurodegeneration in TDP-43 (and FUS) proteinopathies." (PMID 40468389, 2025). "It is noteworthy that, in carriers of SOD1 or FUS mutations, TDP-43 pathology is rarely observed, but their cognate SOD1 or FUS encoded proteinopathy abounds." (PMID 40252666, 2025). "Of the four studied genes encoding ceramidase, the level of mRNA of acid ceramidase Asah1, localized in lysosomes, was the one increasing during the progression of FUS-mediated proteinopathy." (PMID 36836867, 2023). "Our yeast model of FUS proteinopathy has illuminated several genetic modifiers of FUS aggregation and toxicity, which have translated to fly, mammalian cell, and neuronal models of ALS/FTD." (PMID 36529289, 2023). "Considering the apparently complementary pathomechanisms of FUS and TBK1 mutations (in particular impaired protein quality control due to TBK1 haploinsufficiency and FUS proteinopathy as a consequence of FUS mutations), this is a remarkable finding." (PMID 34518945, 2022). "The accumulation of particular misfolded and aggregated proteins (ALS related proteins: TDP-43, SOD1, FUS) play a crucial role in the pathogenesis of the so called “protein misfolding disorder” ALS." (PMID 34439885, 2021). "In particular, purinergic signaling in astrocytes and oligodendrocytes have remained ill-defined, as well as purinergic signaling pathways in proteinopathies involving FUS or TDP-43 aggregates." (PMID 34054698, 2021). "CDI for amyloid beta (Aß) and immunohistochemistry for Aß, alpha-synuclein, TDP-43, and FUS excluded coexistent proteinopathies and other comorbidities." (PMID 32219515, 2020). "Several systems have been used to model FUS-proteinopathies, in all of which wild-type or ALS-mutant FUS overexpression led to progressive neurodegeneration reiterating findings in patients." (PMID 32582692, 2020).
proteinopathies (continued). "In FUS proteinopathies, cytoplasmic accumulation of FUS can be dramatic, leading to the formation of large inclusions sometimes filling the entire cytosolic space." (PMID 31875556, 2019). "Yet in FUS proteinopathies, full-length FUS or FUS with small C-terminal truncations forms cytoplasmic inclusions." (PMID 31875556, 2019). "In ALS-FUS, FUS-positive inclusions are detected in the cytoplasm of neurons and glia, a condition known as FUS proteinopathy." (PMID 31875556, 2019). "Despite the large number of new findings, further studies are required in order to obtain a better understanding of the pathogenesis of FUS-proteinopathies." (PMID 29142303, 2017). "The main aim of the present study was to investigate the eventual role of lncRNAs in the pathomechanisms of FUS-proteinopathies." (PMID 29142303, 2017). "In summary, classification of FUS/FET proteinopathies is based only on morphological criteria; however, distinct stainings with FET proteins can be helpful also when a genetic origin is considered." (PMID 26848654, 2016). "Pathologically, FUS immunoreactive inclusion bodies are detected in a range of neurological diseases classified as FUS-proteinopathies." (PMID 26335776, 2015). "To rigorously test the idea that mutations in FUS alter its assembly into RNP granules, we first explored the biology of FUS in a C. elegans model of FUS proteinopathy." (PMID 26526393, 2015). "To characterize molecular and cellular damages in patients with FUS-proteinopathies, we collected de-identified post-mortem tissue samples from the Cognitive Neurology & Alzheimer's Disease Center at Northwestern University." (PMID 26335776, 2015). "Our study offers a potential explanation for the highly heterogeneous nature and complex genetic presentation of different forms of FUS-proteinopathies." (PMID 26335776, 2015). "Several systems have been used to model FUS-proteinopathies, ranging from yeast to vertebrate animals." (PMID 26335776, 2015). "FUS-proteinopathies, a group of heterogeneous disorders including ALS-FUS and FTLD-FUS, are characterized by the formation of inclusion bodies containing the nuclear protein FUS in the affected patients." (PMID 26335776, 2015). "ALS and FTLD are two neurodegenerative disorders that fall within an overlapping clinical and pathological disease spectrum that includes the TDP-43 and FUS proteinopathies." (PMID 22961620, 2013). "These disorders have now been grouped together as the FUS proteinopathies, because they share a common pathology and a presumed underlying disease mechanism." (PMID 23046583, 2012). "Based on these findings, and the referenced pathological findings in human cases, we suggest that α-internexin and OPTN pathology are downstream events and are not a major driver of pathology and neurodegeneration in most FUS proteinopathies." (PMID 23046583, 2012). "Cytoplasmic mislocalization and inclusion formation are common pathological features of TDP-43 and FUS proteinopathies." (PMID 22919483, 2012). "Finally, future therapeutic strategies that aim to modify the prion-like propagation of pathological TDP-43 or FUS present another promising avenue for development of precision medicine in the context of TDP-43 or FUS proteinopathies." (PMID 40468389, 2025). "Among the 1,495 cases with FTLD where data were available, the underlying proteinopathy was identified as tauopathy in 567 cases (37.93%), TAR DNA-binding protein 43 (TDP-43) proteinopathy in 248 cases (16.59%), and Fused in Sarcoma (FUS) pathology in 8 cases (0.54%)." (PMID 39949536, 2025). "We also use JSF1 to modulate the biophysical states of FUS condensates in live cells and elucidate the relationship between FUS phase transition and FUS proteinopathy, thereby shedding light on the effect of protein phase transition on cellular function and malfunction." (PMID 38971830, 2024).
proteinopathies (continued). "Thus, focal seeded aggregation of FUS and further propagation through prion-like spread elicits FUS-proteinopathy and FTLD-like disease progression." (PMID 38862967, 2024). "In the present study, we report our findings that support an additional shared pathway underlying the detrimental effects of TDP-43 and FUS aggregation in the cytoplasm, and explore a potential therapeutic avenue for the treatment of neurodegenerative diseases with TDP-43 and FUS proteinopathies." (PMID 38111057, 2023). "These interesting differences in the pathophysiological function of CK1 may provide us with clues to the pathomechanism of proteinopathies caused by TDP-43 and FUS." (PMID 35753345, 2022). "When comparing the epidemiological results with the brain autopsies results, it is important to note that FTD is a clinical term; the neuropathological counterpart is Frontotemporal Lobar Degeneration (FTLD) with different causes: TDP-43 proteinopathy, tauopathy or the rarer FTLD (i.e. FUS)." (PMID 33144621, 2020). "Yet even overexpression of ALS-linked FUS mutants in the mammalian CNS is not sufficient to cause overt FUS deposition and proteinopathy." (PMID 31875556, 2019). "These novel results reveal an evolutionarily conserved lncRNA-dependent mechanism to control FUS transcripts, and this may provide new ideas for further research of the pathomechanism of FUS-proteinopathies." (PMID 31546813, 2019). "Thus, conditions characterized by the presence of abnormal FUS inclusions are collectively called FUS proteinopathies." (PMID 31875556, 2019). "FUS is an aggregation-prone hnRNP involved in transcriptional and post-transcriptional regulation that aberrantly forms immunoreactive inclusion bodies in a range of neurological diseases classified as FUS-proteinopathies." (PMID 29142303, 2017). "Indeed, we herein demonstrated that insoluble hFUS in the hsrω RNAi background was negative for ubiquitin making the hFUS inclusions of this study not corresponding to the pathological inclusions observed in human FUS-proteinopathy patients." (PMID 29142303, 2017). "On the other hand, the dynamics of association/dissociation of RNAs with TDP-43 or FUS might contribute to TDP-43 and FUS proteinopathies." (PMID 29109677, 2017). "This recent finding showed that in the absence of mutations, higher FUS levels also represent a critical event in FUS-proteinopathies." (PMID 29142303, 2017). "Our data suggest that one point of such convergence and a critical event in FUS-proteinopathies may be FUS-induced impairment of mitochondria." (PMID 26335776, 2015). "Mitochondrial impairment may be an early event in FUS proteinopathies and represent a potential therapeutic target for treating these fatal diseases." (PMID 26335776, 2015). "Our findings suggest that mitochondrial impairments may be an early or initiating event in FUS proteinopathies." (PMID 26335776, 2015). "Animal models of FUS proteinopathies established by over-expressing Wt- or ALS-mutant FUS recapitulate major clinical and pathological features of FUS proteinopathies, providing useful systems to study pathogenic mechanisms underlying these devastating diseases." (PMID 26335776, 2015). "In all three FUS-proteinopathies cases examined, no FUS mutations were identified and the pathological diagnosis was FTLD-FUS with prominent FUS-positive inclusion bodies detected in the brain tissues." (PMID 26335776, 2015). "Moreover, this deficiency increases with the relative severity of the cytoplasmic accumulation of individual FUS mutants, which would be expected to exacerbate the rate of cytoplasmic accumulation and FUS proteinopathy." (PMID 24204307, 2013). "Despite this ALS-like phenotype, FUS R521C rat lines did not have classic neuropathology associated with FUS proteinopathies." (PMID 23046583, 2012). "These diseases are now called FUS proteinopathies, because they share this disease marker." (PMID 23046583, 2012).